RFC3 (replication factor C subunit 3)
Description:
Subunit of the replication factor C (RFC) complex which acts during elongation of primed DNA templates by DNA polymerases delta and epsilon, and is necessary for ATP-dependent loading of proliferating cell nuclear antigen (PCNA) onto primed DNA.
Synonyms: RFC38; MGC5276
Tractability: Small molecule: a structure with a bound ligand is known. PROTAC: ubiquitination databases record sites on it; its protein half-life has been measured.
Gene: Protein-coding gene on chromosome 13 (33,818,069 to 33,966,558, forward strand). Ensembl gene ENSG00000133119.
Subcellular location: Nucleus
Subcellular location (Human Protein Atlas): Nucleoplasm; Vesicles
Pathways (Reactome):
DNA Repair: Dual Incision in GG-NER; Dual incision in TC-NER; Gap-filling DNA repair synthesis and ligation in GG-NER; Gap-filling DNA repair synthesis and ligation in TC-NER; HDR through Homologous Recombination (HRR); HDR through Single Strand Annealing (SSA); PCNA-Dependent Long Patch Base Excision Repair; Presynaptic phase of homologous DNA pairing and strand exchange; Processing of DNA double-strand break ends; Recognition of DNA damage by PCNA-containing replication complex; Termination of translesion DNA synthesis; Translesion Synthesis by POLH; Translesion synthesis by POLI; Translesion synthesis by POLK; Translesion synthesis by REV1
Cell Cycle: Activation of ATR in response to replication stress; G2/M DNA damage checkpoint; Polymerase switching on the C-strand of the telomere
DNA Replication: Polymerase switching
Disease: Impaired BRCA2 binding to RAD51
Gene Ontology:
Molecular function: ATP-dependent activity, acting on DNA; DNA binding; DNA clamp loader activity; protein binding; single-stranded DNA helicase activity
Biological process: DNA replication; DNA-templated DNA replication; positive regulation of DNA-directed DNA polymerase activity; DNA repair; DNA replication checkpoint signaling; DNA strand elongation involved in DNA replication; DNA synthesis involved in DNA repair
Cellular component: Ctf18 RFC-like complex; DNA replication factor C complex; nucleoplasm; Rad17 RFC-like complex; Elg1 RFC-like complex; nucleus; chromosome; protein-containing complex
Genetic constraint (gnomAD): Loss-of-function variants: 20 observed, 25.19 expected, observed/expected ratio (o/e) 0.79, 90% interval 0.56 to 1.15. The upper end of that interval is the gene's LOEUF score, 1.15, which puts it in group 5 of 6, group 1 being the genes least tolerant of losing a copy. Missense variants: 287 observed, 293.75 expected, observed/expected ratio (o/e) 0.98, 90% interval 0.89 to 1.08. Synonymous variants: 100 observed, 103.56 expected, observed/expected ratio (o/e) 0.97, 90% interval 0.82 to 1.14.
Homologues: Orthologues: dog RFC3 (99% identical), macaque RFC3 (99% identical), chimpanzee RFC3 (99% identical), pig RFC3 (98% identical), mouse Rfc3 (97% identical), rat Rfc3 (97% identical), rabbit RFC3 (91% identical), tropical clawed frog rfc3 (89% identical), zebrafish rfc3 (86% identical), guinea pig RFC3 (60% identical), Drosophila melanogaster RfC38 (59% identical), Caenorhabditis elegans rfc-3 (52% identical). Paralogues in human: RFC4 (26% identical), RFC5 (25% identical), RFC2 (24% identical).
Diseases named in the same sentence as RFC3 in open-access papers:
RFC3 is named in the same sentence as 40 diseases in open-access papers, as found by Europe PMC text mining. Sharing a sentence is not in itself a finding about the gene and the disease. The quoted sentences say what the papers report.
breast carcinoma (5 papers, 2013 to 2025). "This demonstrates that RFC3 is associated with the cell cycle and can influence endocrine resistance in breast cancer by affecting the cell cycle." (PMID 38059884, 2023). "In addition, analysis of the results through an online database revealed that RFC3 expression was significantly associated with poor prognosis in ER+ breast cancer." (PMID 38059884, 2023). "This study suggests that RFC3 may play a key role in tumor metastasis and could be a novel diagnostic marker and potential therapeutic target for drug resistance in breast cancer." (PMID 38059884, 2023). "Taken together, our findings suggest that RFC3 may be involved in endocrine resistance in breast cancer through DNA replication in the cell cycle and is significantly associated with metastasis and progression of breast cancer." (PMID 38059884, 2023). "In the present study, we provide evidence that RFC3 expression is upregulated in resistant breast cancer cells and that RFC3 overexpression leads to poor prognosis in breast cancer patients." (PMID 38059884, 2023). "We also demonstrated that in ER positive breast cancer-resistant cells, knockdown of RFC3 blocked the S-phase of cells and significantly attenuated cell proliferation, migration and invasion." (PMID 38059884, 2023). "The expression of RFC3 was significantly higher in tamoxifen-resistant cell lines than in sensitive lines, and the expression level of RFC3 was significantly increased in recurrent breast cancer tissues." (PMID 38059884, 2023). "In the present study, we used Transwell migration assays to assess the spreading and invasive ability of breast cancer cells and found that RFC3 overexpression enhanced the spreading and invasive ability of breast cancer cells." (PMID 38059884, 2023). "Highly expressed RFC3 has been confirmed to be a predictive gene in Kaposi’s sarcoma, breast cancer, esophageal adenocarcinoma, and hepatocellular carcinoma." (PMID 35483337, 2022). "We also demonstrate that RFC3 overexpression promotes the proliferation, migration and invasion of breast cancer cells, while RFC3 knockdown attenuates the proliferation, migration and invasion of resistant breast cancer cells." (PMID 38059884, 2023). "Furthermore, RFC3 expression was significantly higher in breast cancer-resistant cells than in parental cells, which correlated with the cell cycle." (PMID 38059884, 2023). "Taking all these findings into account, we could conclude that RFC3 was involved in endocrine resistance in breast cancer through the cell cycle." (PMID 38059884, 2023). "RFC3 expression levels were significantly increased in the GEO database of breast cancer drug-resistant microarrays, suggesting that RFC3 may be involved in tamoxifen resistance." (PMID 38059884, 2023). "Furthermore, RFC3 overexpression in ER positive breast cancer cells enhanced cell proliferation, migration and invasion." (PMID 38059884, 2023). "Furthermore, knockdown of RFC3 expression severely impairs the proliferation, invasion and cell cycle progression of drug-resistant cells in breast cancer." (PMID 38059884, 2023). "Additionally, another study highlighted the role of RFC3 in the cell cycle, showing that RFC3 overexpression was present in ET-resistant breast cancer cells but absent in parental cells." (PMID 40244377, 2025).
lung adenocarcinoma (4 papers, 2021 to 2025). A carcinoma that arises from the lung and is characterized by the presence of malignant glandular epithelial cells. "The RFC3, as a crucial component of the DNA replication machinery, has been implicated in various cancers, such as head and neck squamous cell carcinoma and lung adenocarcinoma." (PMID 40666234, 2025). "Although the RFC3 is a tumor suppressor gene, it has been associated with poor survival in triple-negative breast cancer, ovarian tumor, lung adenocarcinoma, esophageal adenocarcinoma, hepatocellular carcinoma, suggesting that RFC3 may be a potential risk oncogenic gene involved in tumorigenesis." (PMID 38504096, 2024). "In lung adenocarcinoma, RFC3 can induce epithelial–mesenchymal transition (EMT) and metastasis of lung adenocarcinoma cells through the Wnt/β‐catenin pathway, and high RFC3 expression may Causes poor prognosis of lung adenocarcinoma." (PMID 33190424, 2021).
acute myeloid leukemia (3 papers, 2016 to 2025). Acute myeloid leukemia (AML) is a group of neoplasms arising from precursor cells committed to the myeloid cell-line differentiation. "According to the study of patients with acute myeloid leukemia (AML), RFC3 was found to be highly expressed in their tumor cells." (PMID 35483337, 2022). "Conversely, RFC3 expression was reduced in kidney chromophobe (KICH), acute myeloid leukemia (LAML), thyroid carcinoma (THCA), and thymoma (THYM), indicating that its regulatory functions may differ by tissue type." (PMID 40980067, 2025). "In acute myeloid leukemia (AML), CREB1 plays a critical role in boosting cell proliferation by regulating RFC3 expression and then promoting the G1/S progression." (PMID 27801665, 2016).
esophageal adenocarcinoma (3 papers, 2014 to 2024). A malignant tumor with glandular differentiation arising predominantly from Barrett mucosa in the lower third of the esophagus. "For example, amplification of RFC3 is frequently found in esophageal adenocarcinoma, while RFC2 is overexpressed in nasopharyngeal carcinoma." (PMID 25407051, 2014).
Fanconi anemia (3 papers, 2013 to 2022). Fanconi anemia (FA) is a hereditary DNA repair disorder characterized by progressive pancytopenia with bone marrow failure, variable congenital malformations and predisposition to develop hematological or solid tumors.
hepatocellular carcinoma (3 papers, 2021 to 2024). A malignant tumor that arises from hepatocytes. "Hepatocellular carcinoma (HCC) and cell proliferation of ovarian tumors are suppressed by shRNA-mediated silencing of RFC3 gene." (PMID 34249670, 2021).
gastric cancer (2 papers, 2021 to 2023). A primary or metastatic malignant neoplasm involving the stomach. "RFC3 mutation and loss of RFC3 expression occur in large fractions of gastric cancer and CRC." (PMID 37821801, 2023). "In the enrichment analysis with “Enrichr” online tool, Gastric Cancer Network2 was of the lowest p-value containing TOP2A and RFC3 genes involved in DNA replication process." (PMID 34249670, 2021).
head and neck squamous cell carcinoma (2 papers, 2025). A squamous cell carcinoma that arises from any of the following anatomic sites: lip and oral cavity, nasal cavity, paranasal sinuses, pharynx, larynx, and salivary glands. "Previous research has demonstrated that RFC3 is markedly overexpressed in various malignant tumors, RFC3 demonstrates elevated expression levels in head and neck squamous cell carcinoma (HNSCC), correlating with tumor progression, reduced survival rates, and the infiltration of immune cells." (PMID 40980067, 2025).
lymphoma (2 papers, 2016 to 2025). A malignant (clonal) proliferation of B- lymphocytes or T- lymphocytes which involves the lymph nodes, bone marrow and/or extranodal sites. "Mutational profiling of 26 coding loci in MSI+ GIT and lymphomas revealed instability in half of the microsatellites, two of them (Rfc3 and Rasal2) shared between both entities." (PMID 27447752, 2016). "In contrast, concentrations of newer lymphoma therapies—such as venotoclax, lenalidomide, decitabine, and ibrutinib were negatively correlated with RFC3 expression." (PMID 40980067, 2025). "The analysis revealed a positive correlation between RFC3 expression and the concentrations of cyclophosphamide and bleomycin, both commonly used in lymphoma treatment, suggesting that elevated RFC3 levels may contribute to resistance against these agents." (PMID 40980067, 2025). "Future investigations incorporating microRNA analyses could provide deeper insights into the post-transcriptional regulation of RFC3 and its impact on lymphoma progression." (PMID 40980067, 2025).
ovarian carcinoma (2 papers, 2022 to 2023). A malignant neoplasm originating from the surface ovarian epithelium. "In recent years, RFC3 overexpression has been shown to have a critical impact on the proliferation, metastasis and prognosis of esophageal adenocarcinoma, hepatocellular carcinoma and ovarian cancer." (PMID 38059884, 2023). "This is consistent with previous studies in which downregulation of RFC3 in ovarian cancer OVCAR-3 cells may lead to S-phase arrest." (PMID 38059884, 2023). "In addition, in the study of ovarian cancer patients, the average survival time of patients with high RFC3 expression levels was only 7.7 months, while that of patients with normal expression was as long as 92.9 months." (PMID 35483337, 2022).
triple-negative breast carcinoma (2 papers, 2024 to 2025). An invasive breast carcinoma which is negative for expression of estrogen receptor (ER), progesterone receptor (PR), and human epidermal growth factor receptor 2 (HER2). "RFC3 plays a significant role in the progression of triple-negative breast cancer (TNBC) by promoting the process of epithelial-mesenchymal transition (EMT)." (PMID 40980067, 2025).
cervical cancer (1 paper, 2025). A primary or metastatic malignant neoplasm involving the cervix. "A recent study examined its function in cervical cancer, revealing that the silencing of RFC3 inhibited cell growth, migration, and invasion." (PMID 40980067, 2025).
cholangiocarcinoma (1 paper, 2025). A carcinoma that arises from the intrahepatic biliary tree (intrahepatic cholangiocarcinoma) or from the junction, or adjacent to the junction, of the right and left hepatic ducts (hilar cholangiocarcinoma). "Additionally, elevated RFC3 expression was found in gastrointestinal cancers such as cholangiocarcinoma (CHOL), colon Adenocarcinoma (COAD), esophageal carcinoma (ESCA), and Stomach adenocarcinoma (STAD)." (PMID 40980067, 2025).
colon tumors (1 paper, 2020). "On the contrary, only one of these genes, RFC3 (replication factor subunit 3), was significantly expressed in colon tumors from AAs." (PMID 32983990, 2020).
colorectal cancer (1 paper, 2017). A primary or metastatic malignant neoplasm that affects the colon or rectum. "Downregulation of RFC3 has been associated with lung-, gastric- and colorectal cancer, but it might also play a role in COPD as oxidative stress due to cigarette smoke induces DNA damage." (PMID 29268739, 2017).
fibrosarcoma (1 paper, 2022). A malignant mesenchymal fibroblastic neoplasm affecting the soft tissue and bone. "In ONCOMINE, the mRNA expression level of RFC3 was up-regulated, which was specifically reflected in fibrosarcoma, leiomyosarcoma, mucosal fibrosarcoma, smooth muscle sarcoma, pleomorphic liposarcoma, and so on." (PMID 35483337, 2022).
leiomyosarcoma (1 paper, 2022). An uncommon, aggressive malignant smooth muscle neoplasm, usually occurring in post-menopausal women. "In Barretina Sarcoma’s dataset, RFC3 was over-expressed than normal in the following sarcomas: 2.413 in myxoid/round cell liposarcoma, 2.257 in myxofibrosarcoma, 2.514 in leiomyosarcoma, and 2.539 in pleomorphic liposarcoma." (PMID 35483337, 2022). "Detwiller sarcoma’s dataset showed that RFC3 expression factor with the increased expression: the change of RFC3 in Round Cell Liposarcoma was 3.588, the change of RFC3 in patients with Synovial Sarcoma was 2.548, and the change of patients with Leiomyosarcoma was 2.624." (PMID 35483337, 2022).
myocardial infarction (1 paper, 2025). Gross necrosis of the myocardium, as a result of interruption of the blood supply to the area, as in coronary thrombosis. "On the basis of these findings, lactylation driven transcription of genes such as E2f2 and Rfc3 may also be a potential therapeutic target for cardiomyocyte regeneration post-myocardial infarction (MI)." (PMID 41160759, 2025).
osteosarcoma (1 paper, 2022). A usually aggressive malignant bone-forming mesenchymal neoplasm, predominantly affecting adolescents and young adults. "In a study on osteosarcoma, it was pointed out that RFC3, CDK1, MAD2L1, NDC80, BUB1, etc. jointly participated in the related links of the disease prognosis of osteosarcoma." (PMID 35483337, 2022).
sarcoma (1 paper, 2022). A usually aggressive malignant neoplasm of the soft tissue or bone. "Meanwhile, the results illustrated that highly expression RFC3 was associated with poor OS in patients with sarcoma, which was statistically significant." (PMID 35483337, 2022). "Using the CCLE database, the results suggested that RFC3 was also highly expressed in human sarcoma." (PMID 35483337, 2022). "Consistent with our analysis, in this study, the RFC3 high expression was found in sarcoma tissue." (PMID 35483337, 2022). "Nevertheless, increased RFC3 and RFC5 mRNA levels were associated with poor OS and RFS in sarcoma." (PMID 35483337, 2022). "In addition, Cancer Cell Line Encyclopedia (CCLE) dataset analysis indicated that RFC1, RFC2, RFC3, RFC4, and RFC5 were elevated expressed in sarcoma cell lines." (PMID 35483337, 2022). "Similarly, we found that mRNA expression levels of RFC2, RFC3, RFC4, and RFC5 from RFC family genes were upregulated in sarcoma tissues." (PMID 35483337, 2022). "The results showed that RFC2, RFC4, and RFC5 were upregulated in sarcoma patients, while the high expression levels of RFC1 and RFC3 were both with no significance." (PMID 35483337, 2022).
X-linked intellectual disability syndrome (1 paper, 2024). "Previously, we identified RFC3 and RFC5 as interacting proteins to FAM50A, the deficiency of which causes an X-linked intellectual disability syndrome." (PMID 39368701, 2024).
ZIKV infection (1 paper, 2021). "Although FAM111A and RFC3 act as nuclear localization-related factors and both played important role in DNA virus replication, whether they are involved in RNA virus such as ZIKV infection remains to be determined." (PMID 34930359, 2021).